IRF3 (interferon regulatory factor 3)
Diseases named in the same sentence as IRF3 in open-access papers (continued):
Sharing a sentence is not in itself a finding about the gene and the disease.
diabetes (15 papers, 2012 to 2025). "Both BM chimeras containing Irf3- or Ifn-β-deficient hematopoietic cells and WT stroma developed diabetes." (PMID 32727064, 2020). "Therefore, IRF3 deficiency results in impaired glucose homeostasis and insulin sensitivity, which eventually leads to the development of diabetes around the age of 8 months." (PMID 34091599, 2021). "STING contributes to diabetes-induced retinal vascular cell injury through the STING/TBK1/IRF3/IFN-β signaling pathway." (PMID 37345657, 2023). "Taken together, these results indicate that the suppression of STING ameliorates diabetes-induced aortic endothelial cell injury through IRF3/NF-κB-mediated inflammatory activation." (PMID 38129863, 2023). "The protein expression levels of STING and p‐IRF3 were increased in the skin tissue of three kinds of patients, especially within the psoriasis with diabetes group when compared with healthy skin tissue samples." (PMID 35174638, 2022). "The expression levels of STING and p‐IRF3 were also significantly upregulated in the skin tissue samples of patients with psoriasis and diabetes." (PMID 35174638, 2022). "Notably, the diabetes-induced increase in nuclear IRF3 and p65 was completely blocked by STING suppression in diabetic STING−/− mice." (PMID 38129863, 2023). "In addition, interferon regulatory factor 3 (Irf3) and IFN-β-deficient mice developed diabetes after EMCV-D infection." (PMID 32727064, 2020). "Irf3 showed a significantly reduced gene expression during STZ-induced diabetes." (PMID 29538462, 2018). "Nevertheless, our data suggest that diabetes-induced retinal capillary lesions may occur through STING/TBK1–regulated REC senescence through the IRF3/IFN-β and NF-κB pathways, making STING pivotal to connecting multiple signaling pathways that contribute to DR pathogenesis." (PMID 37345657, 2023). "The expression of IRF3 in subcutaneous adipose tissues of human morbid obese subjects was shown to be positively correlated with peripheral glucose disposal and was negatively correlated with glycated hemoglobin, an indicator of glycemic control and a clinical marker of the severity of diabetes." (PMID 34091599, 2021). "Compared to the findings in normal mice, FN-γ, SOCS1, STAT3, IFITM3, IRF3, and JAK2 expression was significantly higher in spleen cells from mice with diabetes, suggesting homeostatic inflammation was induced." (PMID 37110462, 2023). "We found the expression of p-IRF3 and p-TBK1 was significantly increased in the retinas of diabetic mice 2 months after the induction of diabetes, prior to the development of microvascular injury." (PMID 37345657, 2023). "To further elucidate the molecular mechanism(s) by which STING promotes diabetes-induced retinal vascular cell injury, we investigated the role of downstream effectors of the cGAS/STING pathway, including TBK1 and IRF3." (PMID 37345657, 2023). "In the skin tissue samples of patients with psoriasis and diabetes, immunohistochemistry showed that the expression levels of STING and phosphorylated IRF3 were also significantly increased." (PMID 35174638, 2022). "In humans, we found that the expression of IRF3 in WAT is positively correlated with peripheral insulin sensitivity and is negatively correlated with severity of diabetes." (PMID 34091599, 2021). "When compared to the normal group, the diabetes model group's mRNA expression levels for LBP, TLR4, MyD88, NF-κB, AP-1, and IRF-3 were significantly higher (p < 0.05); after taurine treatment, we discovered that these mRNA levels had decreased significantly (p < 0.05)." (PMID 38560269, 2024). "We provide evidence that elevated levels of IFN-β are present in the retinas of both human DR donors and diabetic mice and that genetic inhibition of STING abolished diabetes-induced secretion of IFN-β and REC senescence; this correlated with a reduction in the levels of p-TBK1 and p-IRF3." (PMID 37345657, 2023).
diabetes (continued). "Collectively, these results suggest that diabetes-induced REC senescence may be due to the activation of STING and the subsequent increase IFN-β through TBK1/IRF3 signaling." (PMID 37345657, 2023).
lung carcinoma (14 papers, 2009 to 2025). "IRF-3 was also involved in lung cancer that decreased and mutated IRF-3 gene expressions were found in non-small-cell lung cancer (NSCLC) patients, altering the immunoregulatory function in tumorigenesis." (PMID 29100282, 2017). "Depletion of SRSF1 in human A549 lung cancer cells reduces IFN-β through the expression of alternative IRF3 spliced variants, while SF3A1 silencing leads to a decreased induction of pro-inflammatory cytokines by promoting an alternative splice form of MyD88." (PMID 27454487, 2016). "Treating lung cancer models with RBN2397 promotes TBK1 phosphorylation of IRF3, restores type I IFN signaling, and enhances tumor immunogenicity." (PMID 37077937, 2023). "Increased phosphorylation of IRF3 by T3DTD relative to T3DPL was reproduced in A549 human lung carcinoma cells." (PMID 32956403, 2020). "Recently, different expression patterns of IRF-3 were found in lung cancer, leading to the alternation of the immunomodulatory function in tumorigenesis." (PMID 28566697, 2017). "The deficiency of GATA-1 in the tumor was accompanied by high expression of IRF-3, suggesting the potential relationship between decreased GATA-1 and increased IRF-3 in lung cancer cells." (PMID 28566697, 2017). "Therefore, we decided to use a monocyte NF-kB/IRF3 reporter cell system to show how each pathway contributes to the MUFA-HMGB1 influence on the immune response in lung cancer." (PMID 39100092, 2024). "Thus, it is meaningful to investigate how IRF-3 is regulated in lung cancer." (PMID 29100282, 2017). "A study on lung cancer and osteosarcoma showed that for drug-resistant lung cancer cells (A549) and osteosarcoma cells (U-2OS), sulforaphane (SFN) inhibited IRF3 activity by activating autophagy through the Nrf2/HO-1 pathway." (PMID 36090998, 2022). "No significant change of IRF3 protein was observed by polyI:C treatment among all lung cancer cells perhaps because its activity is mainly regulated post-translationally by changes in phosphorylation (data not shown)." (PMID 22194884, 2011). "Similarly, a prior study with two related flaviviruses, Japanese encephalitis and Dengue viruses suggested that IFN-β gene induction in A549 lung carcinoma cells was through NF-κB and RIG-I/IRF-3-dependent pathways." (PMID 19798431, 2009). "However, the mechanism of transcriptional regulation of IRF-3 in lung cancer has not been extensively studied." (PMID 28566697, 2017). "cGAS expression showed no expression difference among lung cancer types, while TBK1 and IRF3 showed a low downregulation only in SCLC tumour samples." (PMID 35794238, 2022). "In contrast, endogenous nuclear IRF3 levels or expression of IRF3 target genes did not increase in human DU145 prostatic carcinoma cells, A549 lung carcinoma cells, HeLa cervix carcinoma cells, and HCT116 colorectal carcinoma cells in response to ISD or cGAMP." (PMID 33790360, 2021).
prostate carcinoma (14 papers, 2007 to 2026). A carcinoma that arises from epithelial cells of the prostate gland. "IFNB1 itself and IRF3 encoding a key transcription factor for its synthesis appeared downregulated in the group of prostate cancers with both alterations, too." (PMID 17280610, 2007). "Additionally, signaling by IRF-3 has been implicated in TLR3-mediated apoptosis in prostate cancer." (PMID 27092172, 2016). "Combining existing reports with the analysis presented in this study, it can be inferred that RORC, AR, LIN28B, IRF9, and IRF3 promoted prostate cancer lineage plasticity through the RTK/RAS pathway." (PMID 38778150, 2024). "It has been reported that nobiletin inhibits the growth of prostate cancer cells by suppressing TLR4/TRIF/IRF3, TLR9/IRF7 and AKT signaling pathways." (PMID 34548474, 2021). "RORC, AR, LIN28B, IRF9, and IRF3 exert promotive roles in prostate cancer." (PMID 38778150, 2024). "We treated C4-2, LNCaP, and Myc-CaP prostate cancer cell lines with ENZ and/or IR and measured IRF3 phosphorylation." (PMID 41542764, 2026). "It negatively regulates tank binding kinase 1 activity, which restrains phosphorylation and activation of the transcription factor IRF3, inhibiting androgen‐induced ADP‐ribosylation of the androgen receptor in prostate cancer and trapping PARP7 within the nucleus." (PMID 38342608, 2024). "To explore the mechanism involved in siRNA-induced toxicity on the two human prostate cancer cell lines, we studied the signaling pathway involving TLR3-mediated activation of interferon regulatory factor 3 (IRF3), which leads to release of IFNβ and generation of an inflammatory response." (PMID 36365241, 2022). "Because IRF3 can also regulate the cell cycle, we queried whether TBK1 activity and IFN signaling are involved in the growth-inhibitory effects of RBN2397 in prostate cancer cells." (PMID 37077937, 2023).
HIV-1 infection (12 papers, 2009 to 2025). The type species of lentivirus and the etiologic agent of acquired immunodeficiency syndrome (AIDS). "HIV-1 infection in the endometrium and cervix induces the production of interferon regulatory factor 3 (IRF-3), which further promotes the production of interferon beta (IFN-β)." (PMID 36297257, 2022). "Together, these results suggest that m6A modifications of HIV-1 RNA evade IFN-I induction and IRF3/7 activation during the early stage of HIV-1 infection in differentiated monocytic cells." (PMID 33690734, 2021). "In fact, there is a transient increase of IRF-3 at 5 days post HIV-1 infection." (PMID 19404407, 2009). "Consistent with TRAF3 upregulation, we found an increase in phosphorylated IRF3 and IRF7 at 7-days post HIV-1 infection, as compared to uninfected control cultures and with 3 dpi-infected cultures, although no significant changes were observed at the transcriptional levels for both IRF3 and IRF7." (PMID 41041557, 2025). "However, in CD4+ T cells we could detect IRF3 phosphorylation after 48 hr of HIV-1 infection." (PMID 23159053, 2012). "As expected, HIV-1 infection was blocked by LEN treatment (10 nM), but was not affected by loss of cGAS, STING, or IRF3." (PMID 38712059, 2024). "To discount this, we have tested the IRF-3 protein levels by Western blotting and found no dramatic degradation of IRF-3 in our MDM during the HIV-1 infection course (data not shown)." (PMID 19404407, 2009). "In contrast to IP-10, expression of IFN-β was robustly attenuated by knockdown of IRF3, IRF5, or IRF7 expression in HIV-1–infected MDMs, suggesting a selective and nonredundant role of IRF5 in mediating a proinflammatory response to HIV-1 infection in macrophages." (PMID 40493408, 2025). "However, it remains unclear how m6A modifications of HIV-1 RNA reduce phosphorylation of IRF3 and IRF7 during early stage of HIV-1 infection." (PMID 33690734, 2021). "HIV-1 infection was previously reported to stimulate type I IFN production through the IRF pathway, which we show is potentiated by Vpx, thus it remains possible that NF-κB responses are impaired in the presence of infection with Vpx, whereas the IRF3/IRF7 signaling remains active." (PMID 33563288, 2021). "When we applied siRNA to knockdown IRF-1, IRF-3, or IRF-7 gene expression in human macrophages, the increase of TRAIL expression by HIV-1 infection was reduced by the IRF-1 and the IRF-7 knockdown, but not by the IRF-3 knockdown." (PMID 19404407, 2009). "This drug successfully prevented IRF3 translocation to the nucleus, but could not prevent G1-to-G0 transitioning, SAMHD1 dephosphorylation, and blockade of HIV-1 infection." (PMID 32209460, 2020).
herpes simplex encephalitis (11 papers, 2017 to 2024). Herpes simplex virus encephalitis (HSE) is caused by the infection of the central nervous system by Herpes simplex virus (HSV) that could have a devastating clinical course and a potentially fatal outcome particularly with delay or lack of treatment. "Gene mutations in nucleic acid sensing components such as TLR3 or its downstream signaling molecules (including UNC93B1, TLR3, TRIF, TRAF3, TBK1, IRF3, etc.)are one of the causes of herpes simplex encephalitis." (PMID 38814453, 2024). "Heterozygous IRF3 variants (c.829G > A; p.Ala277Thr) have been described in herpes simplex encephalitis and peripheral blood mononuclear cells isolated from individuals with IRF3 c." (PMID 34973142, 2022). "A heterozygous mutation of IRF3 (R258Q) in a patient is associated with functional IRF3 deficiencies that led to herpes simplex encephalitis." (PMID 33805458, 2021). "Mutations in IRF3 were reported to cause herpes simplex encephalitis, presumably due to impaired IFN responses to HSV-1 infection." (PMID 32719713, 2020). "Mutations in the IRF3 gene in herpes simplex encephalitis (HSE) patients impaired interferon production and the TLR3-TRIF pathway is the most severely damaged." (PMID 30967139, 2019). "Humans with IRF3 deficiencies are shown to be associated with Herpes simplex encephalitis (HSE)." (PMID 34135889, 2021). "Germline variants in TLR3 pathway genes including TLR3, UNC93B1, TRIF, TRAF3, TBK1, and IRF3, as well as two genes important for type I IFN signaling (IFNAR1 and STAT1), have been linked to increased susceptibility to herpes simplex virus encephalitis (HSE)." (PMID 34199501, 2021). "Variants in TLR3 as well as TRIF, TRAF3, TBK1, IRF3, and NEMO that code for mediators downstream of TLR3, and UNC93B1 that is involved in TLR3 trafficking, all reduce type I interferon signaling and are reported genetic causes of herpes simplex encephalitis (HSE)." (PMID 35126383, 2021).
lung adenocarcinoma (11 papers, 2016 to 2026). A carcinoma that arises from the lung and is characterized by the presence of malignant glandular epithelial cells. "Considering GATA-1s was shown previously to be less functional than the full-length GATA-117, these results demonstrated that suppression of endogenous GATA-1 gene expression might be associated with the up-regulation of IRF-3 in lung adenocarcinoma." (PMID 28566697, 2017). "The effect of M3 on the activation of IRF3 was determined in A549 human lung adenocarcinoma epithelial cells." (PMID 39601535, 2025). "In human lung adenocarcinoma and hepatocellular carcinoma patients, we also found the level of IRF3 had a strong inverse relation to the expression of TCF1 and LEF1." (PMID 33188184, 2020). "We further examined the expression of IRF-3 in human lung adenocarcinoma and adjacent normal tissue." (PMID 28566697, 2017). "We used the search term “IRF-3” and isolated datasets representing lung adenocarcinoma and Cancer vs. Normal Analysis." (PMID 28566697, 2017). "In the comparison analysis, eight datasets showed that IRF-3 RNA expression was over-expressed in lung adenocarcinoma compared to normal tissue." (PMID 28566697, 2017). "IRF-3 mRNA and protein expression were significantly elevated in lung adenocarcinoma compared to adjacent normal tissue." (PMID 28566697, 2017). "In our study, the expression levels of IRF-3 mRNA and protein were higher in lung adenocarcinoma tissue than in adjacent normal tissue, an observation which is consistent with our Oncomine analysis." (PMID 28566697, 2017). "In summary, these data indicate TSA activates IRF-3 transcriptional activity via an acetylation dependent manner in lung adenocarcinoma A549 cells." (PMID 29100282, 2017). "In contrast to the effect of suppression, GATA-1 over-expression caused a dramatic decrease of the promoter activity and protein expression of IRF-3 in different lung adenocarcinoma cell lines." (PMID 28566697, 2017). "Moreover, high expression of IRF3 correlated with favorable survival in colorectal cancer, lung adenocarcinoma, and hepatocellular carcinoma patients." (PMID 35012444, 2022). "Only one study by Wang 37 reported that suppression of endogenous GATA-1 gene expression was found in lung adenocarcinoma, which might be connected with the upregulation of IRF-3." (PMID 34093794, 2021). "Notably, the low expression of IRF3 and the high expression of TCF1 and LEF1 were found to be significantly associated with the poor outcome in CRC and lung adenocarcinoma patients." (PMID 33188184, 2020). "Taken together, we conclude that reduced GATA-1 could be responsible for the upregulation of IRF-3 in lung adenocarcinoma cells through binding with a specific domain of IRF-3 promoter." (PMID 28566697, 2017). "Understanding this molecular mechanism may help to prove that IRF-3 is a useful target in the alternation of tumorigenesis in lung adenocarcinoma." (PMID 28566697, 2017). "But, little is known about IRF-3 transcriptional activity in lung adenocarcinoma." (PMID 28566697, 2017). "We further analyzed the relationship of GATA-1 and IRF-3 expression in lung adenocarcinoma cell lines and found that inhibition of GATA-1 by siRNA increased the promoter activity, mRNA and protein levels of IRF-3, while over-expression of GATA-1 down-regulated IRF-3 gene expression." (PMID 28566697, 2017). "Additionally, higher IRF-3 gene expression was observed in human lung adenocarcinoma, accompanied by aberrant GATA-1 protein expression." (PMID 28566697, 2017). "Thus, we addressed this question and found that suppressed endogenous GATA-1 protein expression increased the promoter activity, mRNA and protein of IRF-3 gene in lung adenocarcinoma cell lines." (PMID 28566697, 2017). "Thus, elucidating the molecular mechanism underlying the transcriptional activation of IRF-3 gene may yield insights into how IRF-3 was involved in lung adenocarcinoma." (PMID 28566697, 2017).